TAS2R39 (taste 2 receptor member 39)
Description:
Receptor that may play a role in the perception of bitterness and is gustducin-linked. May play a role in sensing the chemical composition of the gastrointestinal content. The activity of this receptor may stimulate alpha gustducin, mediate PLC-beta-2 activation and lead to the gating of TRPM5 (By similarity).
Synonyms: T2R39; T2R57
Tractability: Antibody: its Gene Ontology location is reachable by antibodies, with high confidence; UniProt predicts a signal peptide or a membrane-spanning region. PROTAC: a small molecule that binds it is known.
Target class: Membrane receptor; Taste receptor (taste family GPCR); Taste family G protein-coupled receptor
Gene: Protein-coding gene on chromosome 7 (143,183,419 to 143,184,435, forward strand). Ensembl gene ENSG00000236398.
Subcellular location: Membrane
Pathways (Reactome):
Signal Transduction: Class C/3 (Metabotropic glutamate/pheromone receptors); G alpha (i) signalling events
Sensory Perception: Sensory perception of sweet, bitter, and umami (glutamate) taste
Gene Ontology:
Molecular function: bitter taste receptor activity; G protein-coupled receptor activity
Biological process: detection of chemical stimulus involved in sensory perception of bitter taste; G protein-coupled receptor signaling pathway; sensory perception of taste
Cellular component: membrane; plasma membrane
Genetic constraint (gnomAD): Loss-of-function variants: 22 observed, 20.86 expected, observed/expected ratio (o/e) 1.05, 90% interval 0.75 to 1.5. The upper end of that interval is the gene's LOEUF score, 1.5, which puts it in group 6 of 6, group 1 being the genes least tolerant of losing a copy. Missense variants: 362 observed, 419.26 expected, observed/expected ratio (o/e) 0.86, 90% interval 0.79 to 0.94. Synonymous variants: 128 observed, 155.86 expected, observed/expected ratio (o/e) 0.82, 90% interval 0.71 to 0.95.
Homologues: Orthologues: chimpanzee TAS2R39 (99% identical), macaque TAS2R39 (93% identical), pig TAS2R39 (70% identical), dog TAS2R39 (68% identical), guinea pig TAS2R39 (56% identical), mouse Tas2r139 (51% identical), rat Tas2r139 (49% identical), tropical clawed frog tas2r7 (28% identical), tropical clawed frog t2r10 (25% identical), tropical clawed frog t2r2 (25% identical), tropical clawed frog tas2r4 (24% identical), tropical clawed frog t2r6 (23% identical), and 9 more. Paralogues in human: TAS2R40 (54% identical), TAS2R9 (28% identical), TAS2R7 (28% identical), TAS2R41 (27% identical), TAS2R4 (26% identical), TAS2R60 (26% identical), TAS2R42 (26% identical), TAS2R8 (26% identical), TAS2R10 (25% identical), TAS2R13 (25% identical), TAS2R1 (24% identical), TAS2R14 (24% identical), and 11 more.
Diseases named in the same sentence as TAS2R39 in open-access papers:
TAS2R39 is named in the same sentence as 4 diseases in open-access papers, as found by Europe PMC text mining. Sharing a sentence is not in itself a finding about the gene and the disease. The quoted sentences say what the papers report.
colorectal carcinoma (1 paper, 2022). A malignant epithelial neoplasm that arises from the colon or rectum and invades through the muscularis mucosa into the submucosa. "Previous studies already showed that the bitter-tasting compounds diclofenac (TAS2R14) and resveratrol (TAS2R14, TAS2R39) increased the NSAID-activated gene (NAG-1), which was later renamed GDF15, in a human colorectal carcinoma cell line." (PMID 34784295, 2022).
cancer (2 papers, 2014 to 2021). A tumor composed of atypical neoplastic, often pleomorphic cells that invade other tissues.
TAS2R39 also shares sentences with these, for which no sentence is quoted: breast carcinoma (1 paper); cardiovascular disease (1).